BMP4 (bone morphogenetic protein 4)
Diseases named in the same sentence as BMP4 in open-access papers (continued):
Sharing a sentence is not in itself a finding about the gene and the disease.
anemia (13 papers, 2009 to 2024). A reduction in the number of red blood cells, the amount of hemoglobin, and/or the volume of packed red blood cells. "In the case of CI-associated pathology, severe anemia as well as loss in bone marrow cellularity triggers stress erythropoiesis, which requires BMP4 and the formation of stress BFU-E driven by EPO stimulation." (PMID 24587369, 2014). "The BFU-E population increases in a BMP-4 dependent pathway in the spleen and liver during stress erythropoiesis, which is a part of the inflammatory state and a response to anaemia and tissue hypoxia." (PMID 39518858, 2024). "Similar to fetal liver, in response to anemia, BMP4-dependent signaling, which is regulated by hypoxia, initiates the rapid and extensive expansion of erythroid progenitors in the adult spleen." (PMID 35694408, 2022). "Previously it has been shown that in a mouse inflammation model EPO stimulates spleen BMP4-dependent stress-induced erythropoiesis and reduces anemia." (PMID 36457703, 2022). "This pathway is bone morphogenetic protein 4 (BMP4) dependent and is initiated by increased erythrophagocytosis resulting from acute anaemia and inflammatory stress." (PMID 35665597, 2022). "Our study contributes important insights in tumor-induced anemia and tumor-stress erythropoiesis, and indicates that macrophages, BMP4 and Epo are important factors for splenic erythropoiesis in tumor-bearing mice." (PMID 25822717, 2015). "Macrophage depletion by injecting liposomal clodronate decreased the expression of BMP4, inhibited splenic erythropoiesis, aggravated the tumor-induced anemia and suppressed tumor growth." (PMID 25822717, 2015). "In summary, CIP treatment 1) significantly improved survival after CI; 2) partially ameliorated CI-induced severe anemia; 3) increased BMP4 production by F4/80+ macrophages in spleen; and 4) elevated IL-3 concentrations in serum of CI mice." (PMID 24587369, 2014). "In this report, we have characterized the hypoxia dependent regulation of BMP4 expression during the recovery from acute anemia." (PMID 20585586, 2010). "Indian Hedgehog (Ihh) and Desert Hedgehog (Dhh) in the spleen induce the bone marrow progenitor cells to adopt the stress erythroid progenitor cell fate, which makes them competent to respond to BMP4 in response to acute anemia." (PMID 20585586, 2010). "Our present study suggests a model where, in response to acute anemia, expansion of the hypoxia zone in the liver acini leading to an expansion of Hif2α dependent expression of BMP4." (PMID 20585586, 2010). "Tissue hypoxia is present only in response to anemia, and BMP4 expression is also limited to times of anemia." (PMID 20585586, 2010). "Furthermore, macrophage depletion with cloldronate reduced the induction of splenic BMP4, consist with the anemia and the decreased numbers of splenic-stress BFU-E and CFU-E in 4T1 tumor-bearing mice treated with clodronate." (PMID 25822717, 2015). "Here, we hypothesize that the HIF complex is required for regulating BMP4 transcription in the spleen during the recovery from acute anemia." (PMID 20585586, 2010). "Furthermore, we observed that BMP4 expression is delayed in the spleens of flexed-tail (f) mutant mice during the recovery from acute anemia and in the fetal liver of mutant embryos." (PMID 20585586, 2010). "Tissue hypoxia is one of the physiological characteristics of acute anemia; we hypothesized that BMP4 is induced in spleen by HIF after phenylhydrazine- induced anemia." (PMID 20585586, 2010). "In addition to HIF, the role of other transcription factors that may act independently or in concert with HIF to regulate BMP4 expression during recovery from acute anemia is also indicated by our previous work." (PMID 20585586, 2010). "It was further demonstrated that hypoxia, BMP4 and SCF cooperatively regulate the expansion of splenic early erythroid progenitors in response to anemia." (PMID 35694408, 2022).
anemia (continued). "The rapid response to anemia does not involve only SCF, but also Bone Morphogenetic Protein 4 (BMP4)." (PMID 21415991, 2009).
cleft lip (13 papers, 2011 to 2025). Congenital defect in the upper lip where the maxillary prominence fails to merge with the merged medial nasal prominences. "The relationship between BMP4 and lip development is further supported by mutations in individuals with micro form cleft lip (CL) and orbicularis oris defects." (PMID 25662552, 2015). "A missense and nonsense mutations were found in BMP4 gene in a sample of patients from different genetic background (Mongolia, Philippines, United States of America, Colombia, Guatemala, and Europe) diagnosed with subepithelial, microform, and overt cleft lip." (PMID 23227324, 2012). "Although complete inactivation of Bmp4 was fatal during early stages of embryonic development, targeted ablation of Bmp4 function solely in the maxillary mesenchyme and oral epithelium resulted in the development of cleft lip." (PMID 37566033, 2023). "Bilateral cleft lip was presented in all knockout mice for Bmp4 at 12 days after conception, however after 14.2 days only 22% of the embryos showed cleft lip." (PMID 23227324, 2012). "We recently reported the existence of association between nonsyndromic cleft lip/palate (NSCLP) and BMP4 polymorphisms by detecting transmission deviations for haplotypes that include a region containing a BMP4 promoter in case-parent trios." (PMID 22182590, 2011). "The conditional inactivation of Bmp4 in a transgenic mice line results in an isolated cleft lip." (PMID 22182590, 2011). "Eight significant variants associated with craniofacial malformations such as non-syndromic cleft lip and palate, mandibular prognathism, ocular abnormalities, and tooth defects are found in AXIN2, BMP2, BMP4, NOTCH3, PTCH1, SOX10, and WNT10A." (PMID 38785976, 2024). "The Bone Morphogenetic Protein 4 gene (BMP4) is located in chromosome 14q22-q23 which has shown evidence of linkage for isolated nonsyndromic cleft lip with or without cleft palate (NSCL/P) in a genome wide linkage analysis of human multiplex families." (PMID 22514733, 2012).
bladder cancer (12 papers, 2011 to 2025). "BMP4, secreted by bladder cancer cells, also plays a conducive role in fostering the differentiation of mononuclear-macrophages into M2-like phenotypes, which is closely associated with EMT and tumor invasion." (PMID 39606239, 2024). "Previous studies have shown that bladder cancer cells can stimulate BMP4 to induce macrophages and polarize the M2 phenotype, thereby promoting bladder cancer development." (PMID 36030212, 2022). "BMP-4 secreted from bladder cancer cell lines favored the polarization of monocytes and macrophages into the M2 macrophage phenotype." (PMID 32318332, 2020). "In this line, we have recently described that BMP4, produced by bladder cancer cells, induces monocyte differentiation toward a M2 phenotype, leading to the production of cytokines that favour tumour progression." (PMID 31337120, 2019). "In regards to BMP4, there is only one previous report linking it to bladder cancer, which suggests that its expression plays a growth inhibitory role." (PMID 21483740, 2011). "To determine whether stromal Hh response-regulated Bmp expression is involved in bladder cancer growth, we overexpressed Bmp4 in bladder tumor organoids derived from BBN-induced tumors." (PMID 31036156, 2019). "While BMP4 has been shown to induce M2-polarization of macrophages in bladder cancer, we did not observe significant differences in CD68+ or CD163+ macrophage levels between BMP4low and -high PDAC (TC: p = 0.85; TF: p = 0.52)." (PMID 40826447, 2025). "In a study involving 355 bladder cancer patients and non-malignant hematuria patients, urine PCR detection of IQGAP3/BMP4 and IQGAP3/FAM107A showed a sensitivity of 71.0%, specificity of 88.6%, and an area under the curve (AUC) of 0.862." (PMID 40191434, 2025).
osteoporosis (12 papers, 2013 to 2025). A condition of reduced bone mass, with decreased cortical thickness and a decrease in the number and size of the trabeculae of cancellous bone (but normal chemical composition), resulting in increased fracture incidence. "Regarding osteoporosis, several TGF-β superfamily members (TGFB1, BMP2, BMP4, and Sclerostin) have been implicated as candidate genes in osteoporosis." (PMID 33297501, 2020). "Recent studies have found a specific mutation of the Bmp4 gene in patients with dental agenesis, which may be associated with the early onset of osteoporosis and osteopenia in humans." (PMID 34250561, 2021). "Polymorphisms in the BMP4 gene are also demonstrated to be associated with senile osteoporosis." (PMID 24348713, 2013). "It was only recently that DEPTOR was found to play a novel function in osteogenic differentiation by inhibiting MEG3-mediated activation of BMP4 signaling, suggesting its involvement in osteoporosis." (PMID 32390946, 2020). "Together, we demonstrate that Lox/CHOP‐10 crosstalk regulates BMP4‐induced osteogenic and adipogenic fate determination of MSCs, presenting a promising therapeutic target for osteoporosis and other bone diseases." (PMID 30044535, 2018). "Gene assays in the osteoporotic zebrafish model revealed that LC86 significantly boosted the expression of crucial bone metabolism genes, such as sp7, runx2a, bmp2a, bmp4, and col2a1a, which are vital for bone formation, mineralization, and osteoporosis pathogenesis." (PMID 40308595, 2025). "Ectopic expression of circ‐SLC8A1 promoted ALP, BGLAP, SPP1 and BMP4 expression and silenced circ‐SLC8A1 inhibited ALP, BGLAP, SPP1 and BMP4 expression, and it suggested that circ‐SLC8A1 acted as promotive role in the development of osteoporosis." (PMID 34490735, 2021). "FOXO1, BMP4, WNT1, and EGFR in Cluster 2 are related to osteoporosis." (PMID 34777562, 2021).
pancreatic cancer (12 papers, 2011 to 2025). "CHRDL1 exerts tumor-suppressive effects in pancreatic cancer by inhibiting the BMP4/SMAD pathway, reducing migration, invasion, and metastasis." (PMID 40837015, 2025). "As a BMP antagonist, CHRDL1 desensitizes pancreatic cancer cells to BMP-4, thereby inhibiting BMP-mediated SMAD1/5/9 signaling." (PMID 40837015, 2025). "Taken together, the contrast expression patterns of BMP4 in normal pancreas and pancreatic cancer and its prognostic values implied an important role of BMP4 in PAAD." (PMID 41169612, 2025). "By emphasizing its metabolic regulation, prognostic significance, and enrichment in cancer cells and CSCs, this study provides a foundation for future work exploring BMP4 as both a biomarker and a therapeutic target in pancreatic cancer." (PMID 41169612, 2025). "It should be noted that BMP4 was relatively low expressed in pancreas but aberrantly upregulated in pancreatic cancer, implying a potential involvement of BMP4 in the tumorigenesis of pancreatic cancer." (PMID 41169612, 2025). "Instead, they concluded that ATM deficiency enhances pancreatic tumor potential by increasing EMT and BMP4 signaling in precancerous lesions." (PMID 28894253, 2017). "Therefore, we attempted to use recombinant BMP4 protein (2.5 ng/ml) to verify its effects in the progression of pancreatic cancer cells." (PMID 40837015, 2025). "Pancreatic cancer remains highly lethal with poor survival, and whether BMP4 contributes to its progression was unclear." (PMID 41169612, 2025). "Additionally, BMP5 together with BMP4 have a dualistic role in some pancreatic cancer cell lines, acting simultaneously as anti-proliferative factors inhibiting cell growth as well as pro-metastatic factors through stimulation of cell migration and invasion." (PMID 32968094, 2020). "Finally, we applied the BMP4 signalling signature used in our mouse model to stratify pancreatic cancer patients, which have been separated according to their ATM expression levels (high vs low)." (PMID 26220524, 2015). "Notably, SMAD4 - a tumor suppressor gene frequently deleted in pancreatic cancer - may form a feedback loop with BMP4 regulation." (PMID 40837015, 2025). "Interestingly, BMP4 also harbors growth inhibitory properties accompanied by the induction of cell cycle regulator p21/waf1, suggesting redundant roles of these family members which affect pancreatic cancer progression." (PMID 22934011, 2012). "Furthermore, the prognostic significance of BMP4 in pancreatic cancer remains unclear." (PMID 41169612, 2025). "In vitro cultured ovarian and pancreatic cancer cells showed upregulation of SNAIL2 and downregulation of CDH1 upon BMP4 incubation." (PMID 27191723, 2016). "For instance, BMP4- and BMP2- induced MSX2 expression stimulated EMT in pancreatic cancer and cardiac cushion cells, respectively." (PMID 21730974, 2011). "Similarly, a TGFβ family member BMP4 which phosphorylates different Smad (Smad1, 5 and 8) from TGFβ (Smad2 and 3) also induces EMT in pancreatic cancer cells via the induction of MSX2." (PMID 22934011, 2012).
cleft palate (11 papers, 2012 to 2023). Cleft palate is a fissure type embryopathy that affects the soft and hard palate to varying degrees. "Msx1 is also associated with human non-syndromic cleft palate, and msx1-deficient mice have cleft secondary palate as well as reduced expression of bmp4 and shh." (PMID 27741242, 2016). "Loss of the Tp63 gene leads to cleft palate through altering the expression of a variety of genes (including Bmp4) in the maxillary processes from which the palatal shelves emanate." (PMID 23316168, 2012). "This feedback loop is believed to be one of several such feedback loops controlling the expression of BMP4 and BMP4-mediated cell proliferation and migration in the developing palate mesenchyme, as knockout of Tbx3 does not cause cleft palate in mouse models." (PMID 30029495, 2018). "Hoxa2 null mice exhibit an 81% penetrance of cleft palate, which appears to result from increased cell proliferation where expression levels of both Msx1 and its known down-stream target Bmp4 are up-regulated during the early stages of palate development." (PMID 23316168, 2012). "Bone morphogenetic protein 4 (BMP4) is of special interest as it is involved in craniofacial development and an important candidate gene for cleft palate defects." (PMID 27757173, 2016).
heart failure (11 papers, 2010 to 2025). Inability of the heart to pump blood at an adequate rate to meet tissue metabolic requirements. "Bone morphogenetic protein 4 (BMP4) plays an important role in bone remodeling and in heart failure pathogenesis." (PMID 32319199, 2020). "The expression of most of the pro-fibrotic and EndoMT mediating genes like CTGF, SNAI1, SNAI2, Twist 1 and 2, BMP4, and Actn1 are upregulated during heart failure and most of these are down-regulated at Week 19 (recovery)." (PMID 33584806, 2020). "In addition to its significant role in skeletogenesis, BMP4 was revealed to be an important regulator in many diseases, such as Alzheimer's disease, pathological cardiac hypertrophy/heart failure, diabetic nephropathy and multiple cancers." (PMID 33452764, 2021). "It needs to be added that a decrease in BMP4 content after physical activity in tibia in the group of heart failure mice only, might potentially result from an increase in sclerostin level." (PMID 32319199, 2020). "However, a systemic role of BMP4 decrease in tibiae, resulting from the physical activity we applied under the cardiac failure conditions still needs to be verified in our ongoing experiments." (PMID 32319199, 2020). "To investigate whether increased BMP4 levels were associated with increased GPC6 expression after AB in mice and human heart failure, we measured BMP4 mRNA in the LV." (PMID 27768722, 2016). "In the present study, we explored the regulation of glypican expression in cardiac tissue and cells in clinical and experimental heart failure, and investigated interactions between glypicans, BMP4, MAPK signaling, pro-fibrotic and pro-hypertrophic growth processes in cardiac cells." (PMID 27768722, 2016). "Moreover, assuming the pro‐inflammatory function of BMP4, training‐induced decrease in the BMP4 content in bone might have a slowing down impact on the progression of heart failure." (PMID 32319199, 2020). "Since an increase in BMP4 expression leads to cardiac hypertrophy and fibrosis through oxidative stress and apoptosis, a decrease in BMP4 expression in the heart in Tgαq*44 mice after physical training might delay heart failure progression by attenuation of these processes." (PMID 32319199, 2020). "It has also been demonstrated that among BMP family, BMP4 through upregulation of the calcineurin/nuclear‐factor of activated T‐cells (calcineurin/NFAT) pathway promotes cardiac fibrosis and is involved in pathological cardiac hypertrophy, which is a leading cause of heart failure." (PMID 32319199, 2020). "On the other hand, given the proinflammatory function of BMP4, training‐induced decrease in the BMP4 content in bone might be beneficial for the failing heart but further studies are needed to better understand the link between bone metabolism and heart failure." (PMID 32319199, 2020). "Given the suggested interaction between glypicans and BMPs in previous studies, we treated NFB, AFB and NIH 3T3 fibroblasts with BMP4, a BMP isoform important in heart failure." (PMID 27768722, 2016). "Plasma BMP4 levels in heart failure patients are found to be significantly higher in heart failure patients than that of subjects without heart failure." (PMID 36746787, 2023). "In the heart failure mice, qPCR showed no significant change in Bmp2, Bmp4, Nkx2.5, Shox2 and Tbx3 in the sinus node, but there was a significant downregulation of Tbx18 and Isl1 and upregulation of AP1, Mef2c and NRSF mRNA." (PMID 32647133, 2020).